IL10 (interleukin 10)
Diseases named in the same sentence as IL10 in open-access papers (continued):
Sharing a sentence is not in itself a finding about the gene and the disease.
COVID-19 (continued). "Although the p62 blood levels in COVID-19 patients at diagnosis were decreased, they were positively correlated with the amounts of TNF, IL-17, IL-10, and IL-33." (PMID 37174682, 2023). "Ratios of serum levels of IL-10 and Gal-3 with IL-1β, TNF-α and IL-12 in all stages of COVID-19 were made." (PMID 36702907, 2023). "We first showed that MSC transplantation in severe COVID-19 patients led to the elevation of the plasma levels of IP-10, MIP-1α, G-CSF, and IL-10." (PMID 36901868, 2023). "The resolution of cytokine storm was also demonstrated by a substantial decrease in the levels of IFN-γ, IL-10, TNFR-1, and IP-10, all of which are involved in the imbalanced and harmful immune-response typical of severe COVID-19 patients." (PMID 37600829, 2023). "To support this presumption, when correlation analysis was preformed, we found strong positive correlation between percentage of CD4+IL-10+ cells and CD4+FoxP3+ cells in peripheral blood of COVID-19 patients in IV stage." (PMID 37057213, 2023). "We found significantly higher levels of IL-6 (p = 0.002), IL-8 (p = 0.002), IL-10 (p = 0.006) and TNF-α (p = 0.039) in severe COVID-19." (PMID 37969879, 2023). "Concomitantly, in severe COVID-19, an increase in the initial production of IL6 and IL10 (4/6 days) was seen and maintenance of high levels of CXCL8 at times 4/6 and 15/20 days." (PMID 37515295, 2023). "The RS between activation marker concentrations and the severity of COVID-19 are calculated by training data set Z2KP, where the activation markers are IL-17a, IL-2, GATA3, IFN-γ, IL-4, IL-10, PD_1, CD40L, RORγt, CTLA_4, CCR7, TNF-α and IL-6, respectively." (PMID 36845115, 2023). "The aim of this study was to evaluate a COVID-19 vaccine allergy using in vitro T-cell exposure to the tested drug with the flow cytometry measurement of CD69, CD40L, TNFa, IFNG, IL-2, IL-4, IL-6, IL-10, intracellular granulysin, and IFNgamma." (PMID 37686102, 2023). "A previous study showed that the plasma cytokine levels such as IL-6, IL-1β, IL-10, IL-21, and TNF-α were significantly higher in asymptomatic group compared to the controls, indicating an increased inflammation in asymptomatic COVID-19 patients." (PMID 37869674, 2023). "IL-10 and TGF-β levels were higher in COVID-19; in addition, their values were also higher in the severe group." (PMID 38139439, 2023). "For example, increased IL-5, IL-6, IL-10, and MIG but deceased MIP-1β were observed in patients with severe/critical COVID-19 or those admitted to ICU, with satisfactory AUCs for predictive performance." (PMID 37469595, 2023). "In this study, we demonstrated an increase in IL-10, IL-23 and TNF-α in serum samples of COVID-19 patients during mild disease and continue to increase in the severe stage and reach the highest level in the critical phase of the disease." (PMID 37283736, 2023). "Measurement of serum levels of IL-10, TNF-α, INF-γ and TLR-4 showed a highly significant increase in their levels in the COVID-19 patients compared to controls (P value = 0.0001*)." (PMID 36864077, 2023). "In COVID-19-derived monocytes, TNFα, IL1β, IL6, IL10, CXCL8/IL8, and COX2 were also significantly increased, depending on disease severity." (PMID 37310504, 2023). "The mediators IL-1β, IL-6, IL-10, TNF-α, IL-8/CXCL8, IL-1RA, IL-18/IGIF, and sTNFR1 were all increased in patients with COVID-19 and followed the rate of elevation as clinical worsening progressed." (PMID 36851766, 2023). "This study aimed to evaluate the levels of immunological biomarkers such as CRP, C3, C4, IL-8, IL-10, IL-12, TNF-α, and IFN-γ in patients with COVID-19 and bacterial pneumonia." (PMID 38585537, 2023). "Increased anti-inflammatory IL-10 responded to hyperinflammation during SARS-CoV-2 infection and normalized during recovery in post-COVID-19 patients." (PMID 37896963, 2023).
COVID-19 (continued). "In a small cohort of seven MIS-C patients, differentiation between COVID-19 and MIS-C patients was achieved using a combination of IL-10, IL-1RA, IL-18, IL-6, TNF and IFN-gamma." (PMID 37685502, 2023). "Interestingly, recent improvements in the pathophysiologic understanding of COVID-19 revealed that the severity of COVID-19 is strongly associated with cytokine release syndrome (CRS), which is characterized by elevated tumor necrosis factor (TNF-α), interleukin (IL)-6, IL-2, IL-7, and IL-10." (PMID 36770606, 2023). "Our data show that plasma D-dimer concentration in COVID-19 patients was directly related to IL-6 and TNF, and indirectly related to IL-10." (PMID 37408073, 2023). "The highly expressed cytokines in COVID-19 patients included IL-10, IL-6, IL-7, TNF-α, IFN-α, CCL2, and CCL4, but only incubation monocytes with IL-10 downregulated HLA-DR expression." (PMID 36834656, 2023). "Five inflammatory markers were evaluated in the present study, IL-6, IL-8, IL-10, TNF-α, and CRP in hospitalized COVID-19 patients." (PMID 37111039, 2023). "Literature-based data mining and construction of the molecular pathways revealed a total of seven genes connecting ADHD with COVID-19, including CRP, PON1, AR, OXT, IL6, TNFSF12, and IL10.." (PMID 38066446, 2023). "COVID-19 patients with ARDS exhibited higher serum levels of all cytokines and chemokines measured (IFNy, TNFa, IL-4, IL-6, IL-7, IL-8, IL-10, IL-13, MIP-1b, and MCP-1) compared to patients with COVID-19 pneumonia without ARDS (data not shown)." (PMID 37293294, 2023). "Another study demonstrated that the levels of several cytokines (e.g., IL-6, IL-10, and MCP-1) positively correlated with COVID-19 severity; moreover, MCP-1 was correlated with days on mechanical ventilation." (PMID 37081872, 2023). "The secretion of cytokines and chemokines, including IL6, CXCL8, IL1B, IL10 and CCL2, is significantly increased in COVID-19 AKI." (PMID 37274117, 2023). "The aim of this study was to investigate the predictive utility of interleukin (IL)-6, IL-8, IL-10, IL-12, tumor necrosis factor alpha (TNF-α), and interferon gamma (IFN-γ) measurement in patients with COVID-19." (PMID 37969879, 2023). "In our study, we observed a significant positive correlation between increased serum levels of IL-10, IL-23 and TNF-α in COVID-19 patients." (PMID 37283736, 2023). "Higher levels of circulating IL-6, IL-10, IL-8, and tumor necrosis factor-alpha (TNF-α) were detected in non-survivors compared to survivors as well as in severe or critical COVID-19 cases." (PMID 37896963, 2023). "The dysregulated inflammatory responses measured using plasma cytokine concentrations appear different between COVID-19 and CAP, with COVID-19 patients showing higher levels of IP-10, IL-10, and IL-6, and CAP patients had higher levels of GM-CSF." (PMID 36814234, 2023). "A handful of studies have explored the measurement of biomarkers NfL, GFAP, tau proteins, IL-6, IL-10, TNF-α, and CPR during acute COVID-19 and PASC." (PMID 37545721, 2023). "Furthermore, those authors suggested that IL-10 may play a role in the pathogenesis of COVID-19." (PMID 36914565, 2023). "As reported in our prior study, at 13 months after discharge, 11.6% of the HCWs with severe COVID-19 had elevated IL-6, and more than 98% had normal levels of the remaining five cytokines (IFN-γ, IL-10, IL-2, IL-4 and TNF-α)." (PMID 36908474, 2023). "Compared with the control group, there was extensive cytokine/chemokine correlations centered on IL-17A, IL-10, IL-6, CCL2, CXCL8, CXCL9 and CXCL10 and fewer correlations with IL-1β in the COVID-19 patients at baseline." (PMID 37662953, 2023). "Analyses of hospitalized severe COVID-19 patients in other studies have also identified IL-6, IL-10, CCL20, and miR-451a as key factors closely related to COVID-19 mortality." (PMID 38140218, 2023).
COVID-19 (continued). "First, we measured plasma levels of 8 cytokines (IFN-α, IL-1α, IL-1β, IL-10, IL-6, IL-8, S100A8/A9 (calprotectin), and TNF-α), which were shown to be upregulated in the blood of severe COVID-19 patients." (PMID 38082066, 2023). "We found that IL-10 expression by CD4+ T cells was higher in BAL and blood of severe COVID-19 patients." (PMID 37523305, 2023). "Serum levels of IL-23, IL-10, and TNF-α were significantly higher in COVID-19 patients with critical cases compared to mild and severe cases, and correlated positively with CRP level." (PMID 37283736, 2023). "Patients with mild/moderate illness showed significantly higher expression levels of IL-6, IL-1β, IL-10, CRP and IDO1 than COVID-19-free subjects." (PMID 37715121, 2023). "Following treatment with Allocetra–OTS, most of these inflammatory immune-modulators, including IL-6, IFN-γ, IL-10, TNFR1, IP-10, MCP-3, and IL-7, gradually decreased to normal levels with resolution of COVID-19." (PMID 37600829, 2023). "By using canonical correlation analysis (CCA), the gut microbiota composition of 30 patients with COVID-19 was visualized by prognostic groups with five serum cytokines – IFN-γ, IL-2, IL-10, TNF-α, and anti-SARS-CoV-2 S immunoglobulin G (IgG) titers." (PMID 37051240, 2023). "Measurement of IL-10, IL-23, and TNF-α are the best markers for predicting in-hospital mortality in COVID-19; they have potential prognostic values in SARS-CoV-2 infection." (PMID 37283736, 2023). "Individuals with severe and fatal COVID-19 displayed neutrophilia and lymphopenia, as well as increased levels of CRP, ferritin, and cytokines such as IL-6, IL-10, gamma interferon (IFN-γ) and TNF-α." (PMID 36852984, 2023). "Altogether, eight biomarkers stood out as the main inflammatory mediators with discriminative potential between the COVID-19 (recovered/long-COVID-19) and healthy unexposed groups: IFN-γ, IL-10, IL-6, IL-2, IP-10, TNF, IL- 1β, and IL-8." (PMID 37018291, 2023). "Hypertensive COVID-19 patients from both infection waves had significantly higher serum concentration of IL-6, TNF, IP-10, IL-29, IL-8, IL-12p70, IFN-α2, IFN-β, IL-10 and IFN-γ in comparison with controls." (PMID 36817433, 2023). "Other research teams have reported that a significant increase in IL-10 and TNF-α is observed in more severe cases of patients with COVID-19." (PMID 37759873, 2023). "It was reported that COVID-19 patients exhibited high plasma levels of C-C motif chemokine ligand 2 (CCL2), CXCL10, IFN-γ, IL-1β, IL-7, IL-8, IL-10 and TNF-α." (PMID 37251383, 2023). "Compared to HCs, a significant increase in IL-23, IL-10, TNF-α, IFN-γ and MCP-1, were observed in COVID-19 patients." (PMID 37283736, 2023). "Apart from IL-10, MCP-1 was also found to be higher in COVID-19 patients who had previously been vaccinated." (PMID 37629176, 2023). "The up-regulated cytokines (IFN-γ, TNF-α, IL-6, IL-10) in our study indicate induced activation of immune responses against SARS-COV-2 infection and are consistent with other COVID-19 studies." (PMID 38057707, 2023). "Most patients had elevated IL-10, IL-1Ra, IL-2Rα, and TNFR-1, which gradually decreased as COVID-19 resolved." (PMID 37600829, 2023). "IL-2R, IL-6, IL-10 and TNF-α, which were correlated with gender or regions of COVID-19 patients, were finally presented in this study." (PMID 35237162, 2022). "Systemic levels of IL-1β, IL-6, IL-10, IL-23, IL-33 and Gal-1 were significantly higher in stage III of COVID-19 patients compared to stage I and II." (PMID 35075140, 2022). "A study of a longitudinal serum cytokine analysis of 207 COVID-19 patients showed that in very early inflammatory responses, IL-6, TNF-a, IL-10, and IL-1b rose in those with more severe disease." (PMID 35223745, 2022). "Data analysis demonstrated an increased order of magnitude (≥3x) for CXCL8, CCL3, IL-6, IFN-γ, G-CSF and decreased order of magnitude (≤0.3x) for CCL11, IL-4, IL-5, IL-10, PDGF and IL-7 in COVID-19 patients throughout the kinetic follow-up." (PMID 36451835, 2022).
COVID-19 (continued). "A decrease in natural killer T and B cells and increased expression of IL-2, IL6, IL10, TNF-α, and interferon-γ (INF-γ) were observed in the COVID-19 pathophysiology." (PMID 35656183, 2022). "IL-10 significantly downregulated the SARS-CoV-2 specific response of several cytokines, chemokines, and growth factors within both COVID-19 patients and NO-COVID-19-VCs." (PMID 36148228, 2022). "For example, the ratios of TNF-α/IL-5, IFN-α/IL-10, IL-6/IL-5, TNF-α/IL-4, and IFN- γ/IL-5, were lower (≈24-, 23-, 20-, 10-, and 10-fold) in COVID-19 ICU patients as compared with HC subjects." (PMID 36363785, 2022). "The studies indicate that the levels of IL-2, IL-6, IL-7, IL-10, and TNF-α are elevated in COVID-19; moreover, the increased IL-6 levels were found to be associated with disease progression and severe cases." (PMID 35656183, 2022). "In patients with COVID-19 requiring intensive care, low CD4+ and CD8+ cell counts are also detected, negatively correlated with a high expression of cytokines (IL-6, IL-10, and TNF-α)." (PMID 35741174, 2022). "There is a good correlation between IL-10 and INF-γ upon admission, with disease severity and mortality in the COVID-19 patients." (PMID 36286038, 2022). "Cytokine profiles of PBMCs showed significantly lower levels of GM-CSF, IFN-γ, IL-6, IL-9, IL-10, IL-17A, and TNF-α (p < 0.0001) in COVID-19 ICU patients." (PMID 36363785, 2022). "In the study population “B”, we ex-vivo evaluated the immunomodulatory effect of IL-10 at different concentrations (1, 5, and 10 ng/ml) on the SARS-CoV-2-specific peripheral blood cells responses in COVID-19 patients and NO COVID-19-VC subjects." (PMID 36148228, 2022). "We began by examining serum levels of IL-1β, IL-6, IL-10 and TNFα at ICU admission in all serum samples from our Cytokine Cohort of 90 COVID-19 patients." (PMID 36451808, 2022). "From this search, we identified 6 cytokines that are critically involved in the pathogenesis of COVID-19 induced ARDS lung injury (IL-1β, IL-2, IL-6, IL-8, IL-10, and TNFα)." (PMID 35033181, 2022). "MMP-7, TGF-β, CCL2, CCL-3, CXCL-10, G-CSF, IFN gamma, IL-10, IL-2, IL-4, IL-6, IL-7, TNF-α, IL-6, and IGF-1 were studied for their correlation with mortality in all 40 COVID-19 patients." (PMID 36286038, 2022). "The plasma levels of resistin, ICMA-1, IL-6, IL-10 and MCP-1 of the patients with sepsis were statistically higher than those of the patients with COVID-19 at all measurement points." (PMID 35784283, 2022). "Severe COVID-19 patients that develop lung injury showed expanded KLRG1+ Tregs that express Cxcr3, Il10, Il12b1, Ilrb1, Tbx21, Gata3 gene signatures similar to what was found in this study." (PMID 35634302, 2022). "In this study concentrations of TNF-α, IL-1b, IL-2, IL-4, IL-5, IL-6, IL-8, IL-10, IL-12 p70, GM-CSF, and IFN-γ were determined by a magnetic bead assay in tear film collected from 232 symptomatic COVID-19 patients." (PMID 35508669, 2022). "In this study, a considerable rise in serum LDH, troponin I, CK-MB, IL-1β, IL-4, IL-10, IL-17, and INF-γ levels was recorded in COVID-19 patients compared to healthy controls." (PMID 35891209, 2022). "An increase in pro-inflammatory Th17 cells and lymphopenia associated with decreased CD4+ T cells, CD8+ T cells, and natural killer cells, and increased cytokine levels (IL-6, IL-10, and TNF-α) were observed in COVID-19 patients." (PMID 36353605, 2022). "At 10 months after acute COVID-19, poor sleepers similarly showed higher levels of VCAM-1 and IL-10 on T1 blood samples, but higher VCAM-1 and IL-8 levels on T2 blood samples." (PMID 36062000, 2022). "In COVID-19 patients, elevated serum levels of IL-6, IL-1β, TNF- α, IL-10, and CRP have been measured and discussed." (PMID 36268187, 2022). "Increased plasma levels of pro-inflammatory cytokines and chemokines (especially IL-2, IL-6, IL-10, and TNF-α) with impaired IFN-I activation in severe COVID-19." (PMID 36072602, 2022).
COVID-19 (continued). "Elevated inflammatory biomarkers like C-reactive protein (CRP) and proinflammatory cytokines like interleukin-2 (IL-2), interleukin-6 (IL-6), interleukin-10 (IL-10), gamma interferon (INF), and tumor necrosis factor-alpha (α-TNF) are higher in severe COVID-19." (PMID 38013720, 2022). "Besides, in silico models indicate that the mechanism of action of vitamin A against COVID-19 is carried out via modulation of gene expression of key proteins involved in inflammatory reaction and reactive oxygen species production (such as MAPKs, IL10, ICAM1, or PRKCB)." (PMID 35684054, 2022). "Outbreaks of COVID-19 are accompanied by immunocompromised through hyperexpression of both proinflammatory (IL-1, IL-2, IL-6, and TNF-α) and anti-inflammatory (IL-4, IL-10, and IL-17) cytokines, and vice versa with IFN-γ." (PMID 36045713, 2022). "Serum levels of IFNγ, CRP, IL-10, IL-13, IL-6, IP10, MCP-1 and IL-23 were significantly higher in COVID-19 patients than in controls after adjustment for age and BMI." (PMID 36554094, 2022). "Multivariate linear regression analysis of IL-6 and IL-10 according to FT3 with adjustment for age, sex, and BMI in ward hospitalized COVID-19 patients." (PMID 36440226, 2022). "It is suggested that the exacerbated IL-10 production might work as an immune activating agent by for example stimulating the production of other factors of the cytokine storm, thereby amplifying the viral sepsis-related hyperinflammation in critically ill COVID-19 patients." (PMID 35464430, 2022). "Seven out of the 16 known cytokine markers (including IL1A, IL1R1, CCL2, IL6, IL10, CXCL10, and VEGFA) were less pronounced in KD than in severe COVID-19 patients compared to FC and HC, respectively." (PMID 36159873, 2022). "Markedly high levels of notably IL-6, IL-10 and TNF-α have been reported in patients with severe COVID-19." (PMID 35956081, 2022). "Cytokines typical of Th2, Th9, Th17, and Tregs were either low or undetectable, although IL-6, IL-10, and IL-17A levels were higher in peptide-stimulated conditions compared with DMSO control conditions for convalescent COVID-19 participants." (PMID 35044955, 2022). "Specifically, postmortem autopsies from spleens of deceased COVID-19 patients showed that CD8+ T-cells were extremely low in all patients, and inflammatory cytokines (IL-6, IL-8, and IL-10) were increased, along with severe spleen tissue damage." (PMID 36389664, 2022). "In relation to the groups with SIgA, increased levels of IL-10, IL-13, IL-17A, and IFN-α were found in the COVID-19 group as compared to the values observed in the control group." (PMID 35686128, 2022). "The results show that MMP-7, TGF-β, IL-10, IL-7, TNF-α, and IL-6 were significantly correlated with high lung involvement in COVID-19 patients." (PMID 36286038, 2022). "SCD14-ST, as well as the inflammatory markers IL-6, IL-10, SuPAR and sRAGE, were measured in plasma-EDTA of ICU COVID-19 positive patients." (PMID 35740951, 2022). "In agreement with previous studies, our analyses of cytokine profiles revealed different dynamics of IL-2R, IL-6, IL-8, IL-10, and TNF-α during the disease progression of COVID-19." (PMID 35248063, 2022). "A significant increase in 40 analytes was identified, including IL-1, IL-2, IL-6, IL-10, IFN-γ, and TNF-α, which are important proinflammatory cytokines that have been established in patients with COVID-19." (PMID 36290634, 2022). "Our results reported that mothers affected by COVID-19 have an increase in pro-inflammatory factors (TNF-α, IL-2, TGF-β, IL-6 and IL-8) and at the same time, in anti-inflammatory agents such as IL-10, when compared to controls." (PMID 35408809, 2022). "The elevated levels of TNF α, IL-1RA, IL-6, IL-8, IL-10, IP-10, G-CSF and FGF-2 in both patient groups with COVID-19 in our study coincided with previously published studies." (PMID 36012146, 2022). "MMP-7, TGF-β, IL-10, IL-7, TNF-α, and IL-6 were correlated with high lung involvement in COVID-19 patients." (PMID 36286038, 2022).